IL1B (interleukin 1 beta)
Diseases named in the same sentence as IL1B in open-access papers (continued):
Sharing a sentence is not in itself a finding about the gene and the disease.
Obesity (continued). "In this study, with an obesity-related DCM mouse model established by feeding db/db mice with a high-fat diet (HFD), we observed increased mtDNA in the cytosol and activated cGAS-STING signaling pathway during DCM, as well as the downstream targets, IRF3, NF-κB, IL-18, and IL-1β." (PMID 35235096, 2023). "Insulin resistance induced by hyperglycemia and obesity also converges with inflammation and immune modulation in the insulin receptor substrate 1 (IRS-1)/mitogen-activated protein kinase (MAPK)/Akt/phosphatidylinositol-3 kinase (PI3K) and NF-κB/IL-1β/TNF-α/interferon-γ (IFN-γ) pathways." (PMID 37298118, 2023). "Obesity and type 2 diabetes are predominantly related to non-alcoholic fatty liver disease, including accumulation of hepatic triglyceride and increased pro-inflammatory cytokine expression such as IL-1β." (PMID 35937803, 2022). "On the other hand, high plasma levels of IL1β, which is a type of pro-inflammatory cytokine mainly produced by macrophages, may lead to decreased hepatic expression of sex hormone-binding globulin (SHBG) in patients with obesity." (PMID 36065220, 2022). "By studying different media compositions, including media in which we add only one parameter (for instance cytokines such as interleukin-1 beta (IL)-1β and IL-6 and tumor necrosis factor-alpha (TNF-α)), we could be able to link each effect of obesity to one or more factors." (PMID 36278576, 2022). "Moreover, IL-1β mRNA expression at week 8 was significantly higher in the HFDD group than that of the HFV group, indicating the aggravating effect of D-gal-induced aging on increased bone inflammation in obesity." (PMID 35595806, 2022). "Similarly, CaSR over-expression on peripheral blood monocytes or MDM in obesity could lead to increased G protein-coupled receptor (GPCR) signalling and explain the observed increase of [Ca2+]ex-induced IL-1β release." (PMID 35931812, 2022). "Development of asthma was shown to be induced by obesity, as mice fed a high-fat diet (HFD) rapidly developed insulin resistance, hepatic steatosis, airway hyperreactivity, and increased expression of NLRP3 and IL-1β in adipose tissue and the lung as compared with lean mice fed chow." (PMID 35806353, 2022). "The levels of most inflammatory cytokines were elevated on admission in relation to the level that was reached 4–6 weeks later, except for IL-1β, which was lower on admission; these levels were irrespective of the presence of obesity or MS since the cytokine storm masks these inflammatory processes." (PMID 35330391, 2022). "In parallel, there is increasing evidence that pro-inflammatory signals like TNF-α, IL-1β, and IL-6 represent important components of the thermogenic potential of BAT and may lead to their altered capacity for energy expenditure and glucose uptake in obesity." (PMID 35436959, 2022). "However, while it has been shown that certain proinflammatory cytokines such as TNFα and IL-1β induce hepatic IGF-1 resistance, the contribution of IL-6 signaling in obesity-induced inflammation to hepatic insulin and IGF-1 downstream signaling remains controversial." (PMID 35628414, 2022). "Although the regulatory mechanism for this expression is unknown, ANGPTL4 and IL-1β may contribute to the development of atherosclerosis via the induction of local inflammation around EAT in individuals without obesity." (PMID 35566578, 2022). "Moreover, in obesity, inflamed adipocytes create a proinflammatory microenvironment with infiltrating immune cells that foster tumor progression through proinflammatory mediators, such as IL6, IL8 and IL1β." (PMID 34685542, 2021). "Moreover, bulk RNA-Seq revealed an enhanced transcriptional response to LPS at T3 relative to T1 in the lean subjects relative to those with obesity marked by higher expression of pro-inflammatory molecules (IL6, IL1B, TNF) and induction of transcription factors (RELA, IRF1, STAT3)." (PMID 34195568, 2021).
Obesity (continued). "Visceral adipose tissue (VAT) produces higher inflammatory cytokines (TNF-α, IL-6, and IL-1β) in comparison to subcutaneous adipose tissue, suggesting that cytokine storm in COVID-19 infection could be independent of obesity." (PMID 34220807, 2021). "On the contrary to alcohol-free beer, the consumption of traditional beer did not produce any effect on the expression of IL-1β in macrophages when separately analyzing the overweight and/or obesity groups (p = 0.445 and p = 0.672, respectively, Student’s t-test for paired samples)." (PMID 34827151, 2021). "The tumor-killing effector cells (CD8+ T) were suppressed and the immunosuppressor cells (MDSCs/M2) were over-activated to drive their recruitment and suppressive capacity, which could be mediated by obesity-related molecular markers, such as IL-6, CRP, leptin, IL-1β." (PMID 34350120, 2021). "In patients with obesity, overproduction of cytokines evokes a preexisting chronic inflammation, since adipocytes secretion of pro-inflammatory molecules (e.g. MCP-1, IL-6, IL-18, TNF-α, IL-1β) together with a decrease of anti-inflammatory cytokines (e.g. IL-10) has been reported." (PMID 34038475, 2021). "In this way, obesity and mitochondrial dysfunction dysregulate the production of WAT-derived circulating adipokines such as interleukins (IL)-6, IL-1β, and tumor necrosis factor (TNF)-α, which may exacerbate the state of low-grade, chronic inflammation observed in obesity." (PMID 34835983, 2021). "The mechanisms by which IL-1β mediates insulin-resistance have been attributed, at least in part, to downregulation of insulin substrate receptor-1 (IRS-1) and aberrant activity of the transcription factors NF-κB and FOXO1 (Forkhead box protein O1) during obesity or inflammatory conditions." (PMID 33178196, 2020). "In addition, proinflammatory cytokines TNF-α and IL-1β transcript expressions were also detected in the monocytes and macrophages in the mouse adipose tissue SVF, which were well correlated with the reported proinflammatory function of FAS in obesity." (PMID 33488632, 2020). "In the context of obesity, the tumor microenvironment induces an enhanced level of tumor-infiltrating myeloid cells with an activated NLRC4 inflammasome which further activates IL-1b, thus driving progression of disease through adipocyte-mediated VEGFA expression and angiogenesis." (PMID 33167967, 2020). "Finally, we show that targeted deletion of HIF-1α, specifically in myeloid cells, reduced ATM accumulation in the WAT of high fat diet fed mice, as well as local and systemic IL-1β production, implicating HIF-1α as a guardian of metabolic stress and inflammation in obesity." (PMID 32221369, 2020). "We hypothesized that obesity rather than a diet leads to AHR via the IL-1β mechanism and that caloric restriction on the same diet will abolish both AHR and pulmonary inflammation." (PMID 30670753, 2019). "Hence, reprogramming of macrophage responsiveness to LPS in obesity does not seem to rely on inflammasome-dependent mechanisms, at least as far as IL-1β secretion and the time frame covered by the present study (4 h post-LPS) are concerned." (PMID 31316525, 2019). "Leptin stimulates the release of IL-1β in the hypothalamus while a HFD does not appear to upregulate IL-1β in this brain area but IL-1β does increase in the periphery in obesity indicating a more complex relationship between HFD, IL-1β and serpinA3N upregulation." (PMID 30519364, 2018). "In addition, blood-brain barrier (BBB) permeability was increased in a model of obesity-induced by HFD and also aggravated cognitive deficit by increasing the exposure of the brain to various cytokines, including LPS, IL-1β, IL-6, and tumor necrosis factor alpha (TNFα)." (PMID 29316965, 2018).
Obesity (continued). "According to previous studies, HFD intake and obesity induce glia activation and central neural inflammation, as demonstrated by an increase of the gliosis marker GFAP as well as pro-inflammatory mediators (NF-kB, IL-6 and IL-1β) and the infiltration of immune cells." (PMID 30134549, 2018). "In contrast, in obesity, interferon (IFN)-gamma and lipopolysaccharide (LPS) drive the polarization of recruited monocytes toward inflammatory M1-type macrophages and produce a large amount of nitric oxide by expressing inducible nitric oxide synthase (Inos), TNF-α, IL-6, IL-1β, IL-12, and MCP-1." (PMID 28692672, 2017). "Other common genetic variants like the IL-1β promoter region and exon-5 and IL4 -590 T/C single nucleotide polymorphisms, which were not screened in this study, could have association with obesity and its related parameters." (PMID 28293435, 2017). "Since IL-1β is a major contributor to the pathophysiology of obesity in pregnancy and GDM, inhibition of ERS-induced IL-1β synthesis may be a potential therapeutic approach to improve pregnancy complications associated with maternal obesity and GDM, including altered insulin resistance." (PMID 27065887, 2016). "Interestingly, mice with IL-1β, IL-6, or TNFα receptor knocked out show a worsening rather than a reduction in both obesity and metabolic syndrome, suggesting that inflammation is not the only contributing factor to these afflictions." (PMID 26217222, 2015). "IL-1β was not affected significantly by aging nor by obesity (p > 0.05)." (PMID 26604973, 2015). "Obesity reduced caspase‐3 activation without altering caspase‐1 activation, consistent with impaired apoptotic quality control rather than inflammasome‐driven pyroptotic cell death, which is characterized by membrane rupture, IL‐1β release, and chronic inflammation." (PMID 41549510, 2026). "The rapid reduction in IL-1β and TNF-α after 1 month of use of the intervention composition suggests a safe and effective novel strategy for reducing pro-inflammatory cytokines that may offer an opportunity to diminish the inflammatory status in patients with overweight/pre-obesity." (PMID 40430061, 2025). "Furthermore, the chronic low‐grade inflammatory state in obesity results in the infiltration of immune cells, such as macrophages, into the pancreatic islets via the release of proinflammatory cytokines (e.g., TNF‐α and IL‐1β), which can impair β‐cell function and survival." (PMID 38812572, 2024). "In addition, the mRNA expression of pro-inflammatory cytokines TNFα, IL-6, and IL-1β was significantly higher in HFD-fed animals in comparison to STD-fed animals, suggesting that type I gustatory cells can be differentiated into M1-like phenotype of macrophages in obesity." (PMID 37373472, 2023). "Moreover, aerobic exercise could ameliorate obesity-induced inflammation and vascular dysfunction by suppressing NLR family pyrin domain containing 3 (NLRP3) inflammasome, concomitantly reducing the levels of caspase-1 and IL-1β." (PMID 37859981, 2023). "Moreover, IL-6 and IL-1β transcription in mesenteric and periovarian WAT was greatly decreased in both PCOS-like and obese rats after EA treatment, similar to trends in inguinal WAT, indicating that the improvement of chronic inflammation in WAT played a major role in EA-affected obesity." (PMID 35436959, 2022). "Increased IL-1RA secretion could be a possible compensation mechanism or negative feedback for the enhanced release of IL-1β, whose serum level was found to be elevated in diabetic patients, contributing to insulin resistance and progression of atherosclerotic lesions in obesity." (PMID 35163309, 2022). "Third, other than IL-1β mechanisms by which obesity may increase AHR were not addressed." (PMID 30670753, 2019).
Obesity (continued). "Moreover, the biochemical analysis showed that obesity increased the caspase-1 activity and IL-1β production in Asm+/+ mice but not in Asm−/− mice, suggesting the essential role of Asm gene in mediating the obesity-induced NLRP3 inflammasome formation and activation in glomeruli of mice." (PMID 26980705, 2016). "In contrast, IL-1β and CCL2 reflect obesity-related inflammatory burden rather than early metabolic changes, while IL-6 and IL-15 did not reflect early metabolic alterations in this study." (PMID 42196825, 2026). "Higher IL-1β, IL-6, IFN-γ and TNF-α levels were observed in the subgroups with obesity than in the normal weight subgroups, regardless of gender." (PMID 41602164, 2026). "In obesity, a noninfectious inflammatory disease, UBE2M contributes to elevated secretion of the inflammatory cytokines IL-1β, IL-6, and TNF, while its absence leads to reduced levels of these cytokines." (PMID 39675717, 2025). "This demonstrates that the combined impact of PCOS and obesity significantly exacerbates inflammation, unlike in non-PCOS individuals, where BMI has little effect on IL-1β protein levels." (PMID 41411269, 2025). "Not much has been reported about the role of IL‐1β and CXCL16 in regulating the thermogenic effects in obesity." (PMID 38145352, 2024). "In the context of obesity, the priming signals that drive the expression of NLRP3 and pro-IL1b in the AT are not yet clearly identified." (PMID 37239938, 2023). "Cytokines previously associated with increased inflammation, obesity, and metabolic diseases (IL-1β, IL-6, IFN-β, IL-1RA, and IL-17F) were numerically higher but not significantly different in mothers with obesity compared to mothers without obesity." (PMID 38068816, 2023). "In our study, we observed higher IL1B and RETN mRNA in VAT of patients with obesity plus T2DM, rather than in obese patients with a euglycemic state." (PMID 38139276, 2023). "The fact that obesity-associated mediators do not induce S100A9 expression but TNFα and IL-1β do so, suggests an indirect mechanism for the increased S100A9 induction in dWAT and epidermis in the inflamed skin in obesity." (PMID 35198063, 2022). "In summary, the results of our study indicate that subclinical inflammation, in terms of elevated IL-1β and IL-13, appears in PWS patients regardless of overweight or obesity." (PMID 32495042, 2021). "Obesity, regardless of model, is marked by increased levels of a wide array of proinflammatory cytokines, like IL-6, TNF-α, and IL-1β, in the expanding tissues and circulation." (PMID 33554957, 2021). "IL-1β is a major 17.5 kDa pro-inflammatory cytokine secreted mostly by macrophages, and its release from WAT nonfat cells is augmented during obesity." (PMID 34884217, 2021). "Resistin mRNA expression is increased in PBMC from DM2 women, together with increased expression of the inflammatory cytokines IL-1β, TNF-α, and IL-6, independent of obesity." (PMID 19125180, 2008). "IL-1b, IL-6, and TNF were not significantly regulated in monocytes of people with obesity at the investigated time points but it would be interesting to take a closer look pro-inflammatory potential of the lipid droplet positive monocytes in further studies or in a time series-dependent analysis." (PMID 39050851, 2024). "This study represents the first exploration of the effects of the HC and LC exercise protocols, with or without the consumption of BBR, on CRP, IL‐1β, NLRP3, and H19 in middle‐aged men with overweight or obesity and prediabetes, which can be considered an advantage." (PMID 39107107, 2024). "However, no significant roles were observed for IL-1β and TNF-α in our children with OSA and obesity." (PMID 39201638, 2024). "Consequently, obesity affected the levels of all cytokines in the systemic bloodstream, whereby the administration of OEA-DS promoted a decrease in the IL-6 and IL-1β levels, but not TNFα." (PMID 37892420, 2023).
Obesity (continued). "For example, elevated levels of IL-6, IL-1β, and TNF-α mRNAs and reduced expression of brain-derived neurotrophic factor (BDNF) were found in the hippocampus of mice lacking leptin receptor (db/db mice), a genetic model of obesity." (PMID 37373230, 2023). "A high-fat diet induced increased LPS production by Gram-negative bacteria in the gut, while patients with obesity and T2DM were shown to lose weight and have increase insulin sensitivity and reduced NLRP3 and IL-1β expression after reducing their energy supply and exercising." (PMID 36232938, 2022). "MEF explants secreted high levels of several visceral‐associated inflammatory cytokines thought to be important for the negative adipose–muscle signalling in obesity, notably interleukin 6 (IL‐6), monocyte chemoattractant protein 1 (MCP‐1), tumour necrosis factor α (TNF‐α) and IL‐1β." (PMID 35844058, 2022). "How obesity stimulates ILC2s is not yet clear, but it may also involve NLRP3 inflammasome-derived IL-1β since this cytokine is upregulated in obesity and was recently shown to promote the type-2 cytokine production of ILC2s." (PMID 36466877, 2022). "Among diabetes- and obesity-related factors, insulin and insulin-like growth factor 1 down-regulated 11β-HSD1 expression in fibroblasts and myeloid cells, while glucose, fatty acids, TNF-α and IL-1β did not affect it." (PMID 33260645, 2020). "The adipokines with black lettering are those whose circulating levels are enhanced in obesity and whose total release by adipose tissue explants is enhanced in obesity: IL-6, IL-10, ACE, TGFβ1, ICAM-1, TNFα, IL-1β, PAI-1, and IL-8 that are released by nonfat cells." (PMID 20508843, 2010). "However, since ILCs are highly plastic and IL-1β controls ILC2 plasticity, it is also possible that the mixed cytokine phenotype in obesity may reflect ILC plasticity rather than multifunctional memory ILCs." (PMID 36466877, 2022). "However, several are useful biomarkers of systemic dysfunction when unchecked inflammation does not resolve, including angiogenin, IL-1β, IL-6, IL-17, osteopontin, osteoprotegerin, RANTES, TNF-α and TGF-β, linking persistent inflammatory mechanisms to arthritis, type 2 diabetes, obesity and cancer." (PMID 33815289, 2021). "Interestingly, our data suggest that inflammation modulated by IL-1β, IL-6, PLAUR, and CCL2 in the VAT could be related to anxiety and mood disorders as long as patients are not in an obesity state." (PMID 30504920, 2018). "Inflammatory adipokines [IL-6, IL-10, ACE, TGFβ1, TNFα, IL-1β, PAI-1, and IL-8] plus one anti-inflammatory [IL-10] adipokine were identified whose circulating levels as well as in vitro release by fat are enhanced in obesity and are primarily released by the nonfat cells of human adipose tissue." (PMID 20508843, 2010). "Serum TNF-α, IL6, IL1β and MCP-1 levels have been identified upregulated in obese mice and modulated by adipocyte TRPM7 knockout in our study, indicating that adipocyte TRPM7 might be regulated by aberrant cytokines with coupled positive-plus-negative feedback circuits in response to obesity." (PMID 36717580, 2023).